RNU6-109P (RNA, U6 small nuclear 109, pseudogene)
Gene: Small nuclear RNA gene on chromosome Y (16,248,935 to 16,249,041, forward strand). Ensembl gene ENSG00000252173.
Homologues: Orthologues: dog U6 (75% identical). Paralogues in human: RNU6-184P (100% identical), RNU6-1145P (87% identical), RNU6-116P (86% identical), RNU6-1316P (86% identical), RNU6-211P (86% identical), RNU6-310P (86% identical), RNU6-434P (86% identical), RNU6-348P (85% identical), RNU6-38P (85% identical), RNU6-393P (85% identical), RNU6-47P (85% identical), RNU6-698P (85% identical), and 1288 more.